DSG1 (desmoglein 1)
Diseases named in the same sentence as DSG1 in open-access papers (continued):
Sharing a sentence is not in itself a finding about the gene and the disease.
COVID-19 (3 papers, 2022 to 2023). A disease caused by infection with severe acute respiratory syndrome coronavirus 2. "In this study, we have measured desmosomal protein levels and investigated the presence of anti-DSG1, DSG2, and DSG3 antibodies in sera from patients with acute COVID-19 and in those who have recovered from COVID-19 infection." (PMID 37095599, 2023). "We tested the 30 samples from the COVID-19 groups that were positive for skin autoantibodies (intercellular cement staining) by immunofluorescence and found none of these samples were positive for anti-DSG1 or anti-DSG3 autoantibodies." (PMID 37095599, 2023).
head and neck squamous cell carcinoma (3 papers, 2022 to 2023). A squamous cell carcinoma that arises from any of the following anatomic sites: lip and oral cavity, nasal cavity, paranasal sinuses, pharynx, larynx, and salivary glands. "One example is DSG1, a type of desmosomal cadherin, known to be associated with decreased survival in head and neck squamous cell carcinoma." (PMID 34350714, 2022). "Similarly, the upregulation of DSG1, a gene encoding desmoglein-1, has been implicated in the development of several types of cancer, including head and neck squamous cell carcinoma." (PMID 37641095, 2023).
lung carcinoma (3 papers, 2014 to 2020). "Desmoglein-1 is a component of endosomes, and it was reportedly reduced in lung cancer." (PMID 32942548, 2020).
lymph node metastases (3 papers, 1997 to 2020). "Statistically significant predictors of reduced CSS survival were radiation without chemotherapy, large tumour size and lymph node metastases and positive staining for both DSG1 and DSC1." (PMID 22333708, 2012).
pancreatic cancer (3 papers, 2008 to 2022). "A reduction in the amount of the cell adhesion components Dsg1 and Dsg2 in pancreatic tumors suggests that loss of these desmosomal proteins may play a role in pancreatic cancer invasion." (PMID 19091121, 2008). "The expression of Dsg1, Dsg2, and Dsg3 in pancreatic tissues was examined by immunohistochemistry and their expression in two pancreatic cancer cell lines, BxPC-3 and Panc-1, was determined by western blot analysis." (PMID 19091121, 2008). "With both Dsg1 and Dsg2, there was a pronounced shift toward the lower intensity categories in the pancreatic cancer samples." (PMID 19091121, 2008). "A reduction in the amount of the cell adhesion components DSG1 and DSG2 in pancreatic tumours suggests that loss of these desmosome proteins may play a role in pancreatic cancer invasion." (PMID 32850288, 2020). "The pancreatic cancer samples, however, showed an almost complete loss of cells displaying intense (3+) Dsg1 staining and a marked decrease in cells with 2+ intensity with a concomitant increase in cells with weak (1+) or absent (0+) Dsg1 staining." (PMID 19091121, 2008). "All the pancreatic cancer samples displayed an intense desmoplastic response, the synthesis and deposition of collagenous material by stromal myofibroblasts surrounding the adenocarcinoma, and the membrane staining for both Dsg1 and Dsg2 was distinctly weaker in most of the cancer samples analyzed." (PMID 19091121, 2008). "This analysis revealed that the average percentage of cells within each intensity group was similar for Dsg1 between the non-malignant and chronic pancreatitis samples, but that the percentage of more intensely stained cells for Dsg1 decreased markedly in the pancreatic cancer samples." (PMID 19091121, 2008).
skin infection (3 papers, 2018 to 2022). An inflammatory process affecting the skin, caused by bacteria, viruses, parasites, or fungi. "ETs specifically recognize and hydrolyze the cell adhesion molecule desmoglein 1 (Dsg1), causing the dissociation of keratinocytes in human and animal skin and promoting skin infection by S. aureus." (PMID 35878202, 2022).
anal carcinoma (2 papers, 2012 to 2023). "Protein expression of DSG1 was investigated by immunohistochemistry in a cohort of 53 anal cancer patients treated with radiation alone or in combination with 5-fluorouracil and mitomycin C in Myklebust’s research." (PMID 37664033, 2023). "In a cohort of 53 anal cancer patients, DSG1, DSC1 and additionally E-cadherin were analysed at the protein level by IHC." (PMID 22333708, 2012). "They found that DSG1 expression is a prognostic predictor in individuals with anal cancer." (PMID 37664033, 2023). "Protein expression of desmoglein-1 (DSG1), desmocollin-1 (DSC1) and E-cadherin was studied by immunohistochemistry in a cohort of 53 anal carcinoma patients treated by radiation alone or combined with 5-fluorouracil and mitomycin C." (PMID 22333708, 2012). "We have studied the expression of the desmosomal proteins DSG1 and DSC1 in anal carcinoma and their relation to survival." (PMID 22333708, 2012). "Multivariate survival analyses identified DSG1 and DSC1-status to be an independent prognostic variable for CSS in this cohort of anal carcinoma patients when expression of these two proteins was categorised as one variable." (PMID 22333708, 2012).
anal squamous cell carcinoma (2 papers, 2021 to 2022). A squamous cell carcinoma (SCC) arising from the anal canal or the anal margin (perianal skin). "Negative expression of DSG1 on the cell membrane can be used as a marker for anal squamous cell carcinoma." (PMID 33624385, 2021).
atopic dermatitis (2 papers, 2013 to 2024). "Furthermore, in atopic dermatitis, corneodesmosomal proteins such as desmoglein 1 and desmocollin 1 exhibited elevated levels compared with normal or non-lesional skin, indicating increased cell-to-cell adhesion, which may have a relation to the regulation of H2 expression in atopic dermatitis skin." (PMID 39420441, 2024).
cardiac arrhythmia (2 papers, 2015 to 2021). Any disturbances of the normal rhythmic beating of the heart or MYOCARDIAL CONTRACTION. "In patients with PV we didn't find statistically significant differences with respect to levels of anti-Dsg1 autoantibodies, when the groups were divided by age, coronary heart disease and cardiac arrhythmia." (PMID 25896794, 2015). "In patients with PV we didn't find statistically significant differences with respect to anti-Dsg1 autoantibodies levels when subdivided by age, coronary heart disease and cardiac arrhythmia." (PMID 25896794, 2015). "An age of onset ≥ 65 years, presence of coronary heart disease, cardiac arrhythmia and a level of anti-Dsg1 autoantibodies ≥ 100 U/mL at diagnosis were found to be related to overall mortality in patients with PV." (PMID 25896794, 2015).
Chagas disease (2 papers, 2020 to 2022). A parasitic infection caused by Trypanosoma cruzi. "Some rural populations in Brazil chronically exposed to insect bites, such as blackflies and reduviid (vector of Chagas disease) exhibit an autoantibody response against Dsg1.Interestingly, approximately 50% of the normal population possess nonpathogenic anti-Dsg1 autoantibodies." (PMID 35281450, 2022).
eosinophilia (2 papers, 2025). "In this case, the marked elevation of anti-Dsg1, eosinophilia, and dermal eosinophilic infiltrate suggest that IL-17A inhibition may have downregulated the Th1/Th17 axis, relieving inhibition of Th2 cells and promoting IL-4/IL-13 elevation." (PMID 41000395, 2025). "Our study unequivocally demonstrated the existence of EoE variants without eosinophilia detectable in histopathological examination, with immunohistochemical assays for eotaxin-1 and desmoglein-1 potentially aiding in the diagnosis of these variants." (PMID 40284218, 2025).
Pruritus (2 papers, 2016 to 2025). Pruritus is an itch or a sensation that makes a person want to scratch. "Elevated anti-Dsg3 associated with mucosal lesions, anti-Dsg1/anti-Dsg3 associated with Nikolsky sign, while anti-BP180/anti-BP230 levels were linked to pruritus." (PMID 40661962, 2025). "Patients with mucosal lesion and Nikolsky sign had higher levels of anti-Dsg1 and anti-Dsg3 antibodies, and patients with pruritus had higher levels of anti-BP180 and anti-BP230 antibodies." (PMID 40661962, 2025). "Autoantibody levels correlated with disease severity and clinical symptoms, with elevated levels of anti-Dsg3 associated with mucosal lesions, anti-Dsg1/anti-Dsg3 associated with Nikolsky sign, and elevated anti-BP180/anti-BP230 levels linked to pruritus." (PMID 40661962, 2025). "Autoantibody levels correlated with disease severity and specific clinical symptoms, with elevated anti-Dsg3 associated with mucosal lesions, elevated anti-Dsg1/anti-Dsg3 associated with Nikolsky sign, and elevated anti-BP180/anti-BP230 levels linked to pruritus." (PMID 40661962, 2025).
pterygium (2 papers, 2022 to 2025). A wedge-shaped fibrovascular lesion arising from the bulbar conjunctiva and extending to the cornea. "In addition, interestingly, there was an increased FABP5 mRNA expression without an increased FABP5 protein expression, parallel to a decreased PAX6 and DSG1 expression in conjunctival IC samples and in corneal epithelium of pterygium patients." (PMID 40094891, 2025). "PAX6, DSG1, miR-138-5p, and miR-204-5p expression is decreased in the corneal epithelium of epithelial basal membrane dystrophy, Salzmann nodular degeneration, and pterygium subjects." (PMID 40094891, 2025). "In corneal epithelial samples, PAX6 protein, DSG1 mRNA and protein, miRNA-138-5p, and miR-204-5p expression were significantly lower in EBMD, SND, and pterygium samples than in controls (p ≤ 0.02)." (PMID 40094891, 2025). "In the corneal epithelium, we found a decreased PAX6 protein expression and decreased DSG1 mRNA and protein expression in EBMD, SND, and pterygium samples." (PMID 40094891, 2025). "The current results, which show DSG1 mRNA and protein expression decrease in EBMD, SND, and pterygium, correlate well with the clinical observation that EBMD, SND, and pterygium subjects suffer from recurrent corneal erosions." (PMID 40094891, 2025). "Interestingly, our measurement results in EBMD, SND, and pterygium in central corneal epithelial cells show similarities with limbal epithelial cells in AAK, particularly PAX6 and DSG1 mRNA and protein expression." (PMID 40094891, 2025). "However, both DSG1 mRNA and protein expression were significantly lower in EBMD, SND, and pterygium samples compared to controls (p ≤ 0.016 for all)." (PMID 40094891, 2025). "In active pterygium, genes involved with immune and inflammatory response (CXCL9 and PLA2G2D), angiogenesis (SERPINB5 and BM4), keratinization (DSG1), response to UV light (TYR) and negative regulation of apoptotic process (PIM1) are up regulated in relation to atrophic pterygium." (PMID 34997134, 2022). "Additionally, we could detect a decreased DSG1 mRNA expression in EBMD, SND, and pterygium in corneal epithelial cells and a correspondingly decreased protein expression." (PMID 40094891, 2025).
subcorneal pustular dermatosis (2 papers, 2021 to 2023). A rare, benign, chronic disease characterized by sterile pustular eruption, typically involving the flexural sites of the trunk and proximal extremities. "In addition to the presence of four desmosomal Dsg isoforms, i.e. Dsg1‐4, Dsc1, 2 and 3, all of which are derived from different genes, Dsc1 has been previously identified as the target antigen of IgA autoantibodies in the subcorneal pustular dermatosis (SPD)‐type of intercellular IgA dermatosis." (PMID 36578135, 2023).
vulvovaginal candidiasis (2 papers, 2017 to 2022). Infection of the vulva and vagina with a fungus of the genus CANDIDA. "A GWAS study of patients with common infections revealed a significant association between DSG1 variants and susceptibility to vulvovaginal candidiasis." (PMID 36733397, 2022). "We found GWS associations between vulvovaginal candidiasis and variants in DSG1 (rs200520431, P = 1.87 × 10−16, effect = 0.11)." (PMID 28928442, 2017).
-only disease (1 paper, 2020). "Clinical variants include mucosal-only disease (which correlates with circulating anti-Dsg3 autoantibodies), cutaneous-only disease (anti-Dsg1 antibody predominant), or more frequently, mucocutaneous involvement (presence of both anti-Dsg1 and anti-Dsg3 antibodies)." (PMID 32642305, 2020).
abscesses (1 paper, 2024). "However, the exotoxin was species-specific in its digestion of Dsg1, which caused only abscesses in mice after infection." (PMID 39598475, 2024).
adenoma (1 paper, 2020). A neoplasm arising from the epithelium. "Among the 10 adenoma tissues, positive expression of DSG1 was 8 (80.0%) and of DSG2 was 8 (80.0%), respectively." (PMID 32850288, 2020). "Furthermore, peritumoral tissues and adenoma with positive DSG1 and/or DSG2 expression exhibited moderate to severe dysplasia." (PMID 32850288, 2020). "Adenoma and peritumoral tissues with negative DSG1 and/or DSG2 protein expression exhibited atypical hyperplasia." (PMID 32850288, 2020). "Thus, the frequency of DSG1 and DSG2 proteins was calculated in EHCC tumour tissues, peritumoral tissues, adenoma tissues, and normal biliary tract tissues using immunohistochemical staining to evaluate whether the expression of DSG1 and/or DSG2 had any clinical or pathological significance in EHCC." (PMID 32850288, 2020).
alopecia (1 paper, 2023). Hair loss usually from the scalp. "Alopecia, erosions, and blistering were observed in the skin of DSG1, DSG3 and DSG1/DSG3 models, while lesions in the mucosa were observed only in DSG3 and DSG1/DSG3 animals." (PMID 37237515, 2023).
aniridia (1 paper, 2021). Aniridia is a congenital ocular malformation characterized by the complete or partial absence of the iris. "DSG1 (Desmoglein-1) is a cellular junction protein, and it has been reported to be downregulated in Sey+/− (Pax6+/−) mice, which is an animal model for congenital aniridia." (PMID 34827649, 2021).
aphthous ulceration (1 paper, 2022). "Using ELISA, the authors found out in this retrospective study that the level of both anti-Dsg1 and anti-Dsg3 IgG antibodies was significantly higher in patients with erosive OLP compared to healthy control (HC), patients with recurrent aphthous ulceration, and patients with non-erosive OLP." (PMID 36263026, 2022).
Buruli ulcers (1 paper, 2013). "Such specific production of ETA by Buruli ulcers may be explained by the fact that ETs are known to be serine active proteases, with their activity highly specialized for desmoglein-1, an important epidermal protein." (PMID 23924370, 2013).
cardiomyopathy (1 paper, 2019). A disease of the heart muscle or myocardium proper. "In all reported PPKs cases where DSG1 gene variants (frameshift or nonsense) have been reported, there is evidence that affected protein haploinsufficiency leads to the striate, focal PPK and striate PPK with wooly hair and cardiomyopathy." (PMID 31443639, 2019).
cataract (1 paper, 2025). Partial or complete opacity of the crystalline lens of one or both eyes that decreases visual acuity and eventually results in blindness. "The results indicated that patients who developed cataracts as an adverse drug reaction had a significantly higher likelihood of persistent anti-Dsg1 antibody positivity (OR = 37.67; 95%CI: 1.88-756.27, P = 0.018)." (PMID 40433384, 2025). "The presence of Cataracts may indicate persistent anti-Dsg1 positivity after CR, while elevated anti-Dsg3 titers and PDAI scores at baseline may predict sustained elevated anti-Dsg3 post-CR." (PMID 40433384, 2025).
cervical disease (1 paper, 2017). "From our analysis, DSG1, KDR, and SERPINB3 expression may have potential as robust markers that can risk-stratify cervical disease, i.e., identify cervical disease cases that have a high probability of regression, and this would be of significant clinical value." (PMID 29021401, 2017).
cholera (1 paper, 2019). "Although Dsg1 is 65% homologous to Dsg3, only two mAbs had binding activity toward Dsg1, while no mAbs cross reacted with influenza or cholera proteins." (PMID 31340153, 2019).
chronic asthma (1 paper, 2019). An asthma that is characterized by the development of persistent airway inflammation and recurrent attacks of breathlessness and wheezing, which vary in severity and frequency. "Considering DSG1-associated epithelial barrier dysfunction is pivotal in skin and mucosal inflammatory diseases, it is highly possible that the abnormal expression of this desmosomal cadherin at bronchial epithelium might also contribute to the pathogenesis of chronic asthma." (PMID 32076408, 2019).
dementia (1 paper, 2024). Loss of intellectual abilities interfering with an individual's social and occupational functions. "Four protective proteins (PLEK, DAPP1, CSK and CASP3) that decreased postinfection in the BLSA were significantly decreased in dementia cases in the ARIC study, with several other protective proteins (EIF4A1, DSG1, PIK3CG, PRKCB and LYN) showing similar trends." (PMID 39143319, 2024).
ectodermal dysplasias (1 paper, 2010). "Mutations found in PKP1, DSG1, PG, or DP give rise to symptoms typical of ectodermal dysplasias, while autoantibodies against desmosomal proteins induce Pemphigus Vulgaris or Pemphigus Foliaceus, accompanied by blisters in the oral mucosa and/or skin." (PMID 20628490, 2010).
Ellis-van Creveld syndrome (1 paper, 2026). Ellis-van Creveld syndrome (EVC) is a skeletal and ectoderlam dysplasia characterized by a tetrad of short stature, postaxial polydactyly, ectodermal dysplasia, and congenital heart defects. "The diagnoses of patients carrying pathogenic variants unrelated to IEI included primary ciliary dyskinesia, Ellis-van Creveld syndrome, desmoglein-1 deficiency, and others." (PMID 41784637, 2026).
epidermolysis bullosa (1 paper, 2014). Epidermolysis bullosa (EB) is a group of genetic skin diseases that cause the skin to blister very easily. "Cardiovascular and other systemic disorders have been reported in severe systemic skin diseases including psoriasis, epidermolysis bullosa (EB), hidradenitis suppurativa, atopic dermatitis (AD) and desmoglein-1 deficiency." (PMID 25119884, 2014).
gastroesophageal reflux disease (1 paper, 2021). A chronic disorder characterized by reflux of the gastric and/or duodenal contents into the distal esophagus. "Consistently, DSG1 expression is decreased in EoE biopsies, but not in gastroesophageal reflux disease (GERD) biopsies." (PMID 34943362, 2021).
Harlequin ichthyosis (1 paper, 2022). Harlequin ichthyosis (HI) is the most severe variant of autosomal recessive congenital ichthyosis (ARCI; see this term). "Interestingly, some of these genes, i.e. KRT1, KRT9, KRT16, DSG1, DSC2 and JUP, are mutated in hereditary PPKs, while the ABCA12 gene is defective in harlequin ichthyosis characterized by the loss of the skin lipid barrier." (PMID 35854363, 2022).
hyper-IgE syndrome (1 paper, 2025). A condition that is characterized by elevated serum IgE, dermatitis, and respiratory infections. "We report a case of T-cell lymphoma with congenital IV caused by a DSG1 mutation associated with hyper-IgE syndrome (HIES)." (PMID 39949400, 2025). "Here, we report a case of T-cell lymphoma with congenital IV caused by a desmoglein 1 (DSG1) gene mutation associated with hyper-IgE syndrome (HIES)." (PMID 39949400, 2025).
Hyperkeratosis (1 paper, 2020). Hyperkeratosis is a histopathological term defining a thickened stratum corneum and may be present in many different skin conditions, with many possible overlaps. "In this study, we identified a homozygous DSG1:c.2541_2545delGGGCT frameshift variant in a Rottweiler dog with severe footpad hyperkeratosis." (PMID 32344723, 2020).
keloid (1 paper, 2022). An irregularly shaped, elevated mark on the skin caused by deposits of excessive amounts of collagen during wound healing. "Moreover, several proteins that play a role in cell junctions were also downregulated in keloids, including EVPL, PPL, DSP, PKP1, PKP3, DSC1, DSG1, and FLG." (PMID 35435317, 2022).